GLB1L2 (galactosidase beta 1 like 2)
Description:
Probably cleaves beta-linked terminal galactosyl residues from gangliosides, glycoproteins, and glycosaminoglycans.
Synonyms: MST114; MSTP114
Tractability: Antibody: UniProt places it where antibodies can reach, with high confidence; UniProt predicts a signal peptide or a membrane-spanning region; its Gene Ontology location is reachable by antibodies, with medium confidence. PROTAC: ubiquitination databases record sites on it.
Gene: Protein-coding gene on chromosome 11 (134,331,886 to 134,378,341, forward strand). Ensembl gene ENSG00000149328.
Subcellular location (Human Protein Atlas): Nucleoplasm; Vesicles; Predicted to be secreted
Pathways (Reactome):
Metabolism: CS/DS degradation; Glycosphingolipid catabolism; Keratan sulfate degradation
Gene Ontology:
Molecular function: protein binding; beta-galactosidase activity; hydrolase activity, hydrolyzing O-glycosyl compounds
Biological process: galactose catabolic process; carbohydrate metabolic process
Cellular component: vacuole
Genetic constraint (gnomAD): Loss-of-function variants: 56 observed, 68.51 expected, observed/expected ratio (o/e) 0.82, 90% interval 0.66 to 1.02. The upper end of that interval is the gene's LOEUF score, 1.02, which puts it in group 4 of 6, group 1 being the genes least tolerant of losing a copy. Missense variants: 689 observed, 755.31 expected, observed/expected ratio (o/e) 0.91, 90% interval 0.86 to 0.97. Synonymous variants: 266 observed, 297.65 expected, observed/expected ratio (o/e) 0.89, 90% interval 0.81 to 0.99.
Homologues: Orthologues: chimpanzee GLB1L2 (99% identical), macaque GLB1L2 (98% identical), guinea pig GLB1L2 (85% identical), rabbit GLB1L2 (85% identical), dog GLB1L2 (80% identical), mouse Glb1l2 (79% identical), pig GLB1L2 (78% identical), rat Glb1l2 (77% identical), tropical clawed frog glb1l2 (56% identical), zebrafish si:dkey-224e22.2 (52% identical), Drosophila melanogaster Ect3 (33% identical), Caenorhabditis elegans bgal-1 (32% identical), and 3 more. Paralogues in human: GLB1L3 (58% identical), GLB1 (38% identical), GLB1L (36% identical).
Diseases named in the same sentence as GLB1L2 in open-access papers:
GLB1L2 is named in the same sentence as 4 diseases in open-access papers, as found by Europe PMC text mining. Sharing a sentence is not in itself a finding about the gene and the disease. The quoted sentences say what the papers report.
prostate carcinoma (3 papers, 2023 to 2024). A carcinoma that arises from epithelial cells of the prostate gland. "Conversely, decreased expression of GLB1L2 and TRAK2 has been documented in prostate cancer and osteosarcoma, respectively." (PMID 38951817, 2024).
tumor (2 papers, 2023 to 2024). "Paradoxically, a group of proteins, including C1QL3, EPB41, SNX10, FGF14, GLB1L2 and TRAK2, have been reported as good prognostic markers or tumor suppressors in the NmFMC group." (PMID 38951817, 2024).
GLB1L2 also shares sentences with these, for which no sentence is quoted: lung adenocarcinoma (1 paper); osteosarcoma (1).